HSP90AB1 (heat shock protein 90 alpha family class B member 1)
Diseases named in the same sentence as HSP90AB1 in open-access papers (continued):
Sharing a sentence is not in itself a finding about the gene and the disease.
cancer (continued). "For example, HSP90AB1, an oncogene, was upregulated in 8 cancer types, while DNAJB4, a tumor suppressor, was down-regulated in 12 cancer types." (PMID 33225964, 2020). "Based on the Oncomine database, we found that mRNA expressions of TCP1, CCT2, CCT6A, CCT7, STIP1 and HSP90AB1 were significantly upregulated in cancerous samples compared with normal samples in various types of cancer, including BC." (PMID 32194784, 2020). "Although further studies need to be carried out, these results collectively demonstrated that the role of LRP5 is essential in Hsp90ab1-mediated cancer metastasis." (PMID 30305727, 2019). "One set includes glycolysis enzymes as well as HSP90AB1 and YWHAZ (14-3-3ζ), both of which are associated with protein-folding and promote tumour formation and cancer cell proliferation." (PMID 31560702, 2019). "Growing evidence has revealed that Hsp90ab1 overexpression occurs in various different cancers, and this overexpression plays an integral role in the multistep processes leading to carcinogenesis and invasion." (PMID 30305727, 2019). "Our findings support a direct role for USP22 as an essential component of the SAGA complex in promoting the expression of HSP90AB1 during cancer development and progression." (PMID 31801945, 2019). "Together, these findings suggest that USP22 is required for high level expression of HSP90AB1 protein levels both in human cancer cell lines in vitro as well as in murine epithelium and tumors in vivo." (PMID 31801945, 2019). "In particular, the TERT branch is affected by p21 (PTGES3) in LS-CRC, while in s-CRC cancers, we observe high influence of heat shock proteins (HSP90AB1 and HSPA1A)." (PMID 31750255, 2019). "It is well known that Hsp90ab1 is a molecular chaperone that is required for the formation, stability and function of its client proteins, many of which promote cancer cell growth and survival." (PMID 30305727, 2019). "Screening the top 200 genes with monotonic expression against the Cancer Gene Census yielded a completely different set of six genes: HSP90AB1, ALDH2, ESR1, PPP2R1A, HIST1H4I, SEPT5." (PMID 31277598, 2019). "Hsp90ab1 is upregulated in numerous solid tumors, which is thought to induce the angiogenesis and promote cancer metastasis." (PMID 30305727, 2019). "In the present study, we demonstrated that Hsp90ab1 was upregulated in GC cells, which resulted in significantly worse patient outcomes and higher cancer metastasis rate." (PMID 30305727, 2019). "HSP90AA1 and HSP90AB1 facilitate oncogene addiction, critical for cancer progression." (PMID 39796173, 2025). "HSP90AB1 also binds to various proteins, such as steroid hormone receptors, transcription factors, kinases, and ubiquitin ligases, to affect proliferation, metastasis and invasion in cancers." (PMID 38542474, 2024). "However, inhibition of HSP90AB1 in cancer cells leads to extensive degradation of oncogenic proteins." (PMID 37180757, 2023). "Furthermore, we treated cells with cisplatin, ME, or both, and the expression of cancer pathway factors was assessed, including HSP90AB1, IGF1R, p-H2AX, MYC, and PTEN." (PMID 37180757, 2023). "In this study, we observed that DSCC1 interacted and coexpressed with HSP90AB1 in LUAD which promoted cancer progression, indicating that HSP90AB1 might act as a molecular chaperone and be involved in DSCC1-promoted LUAD progression." (PMID 37742009, 2023). "Activation of WNT signaling in osteoclasts, osteoblasts, and cancer cells resulted in their conversion to tumor-suppressive cells with secretomes enriched with Hsp90ab1, enolase 1 (Eno1), moesin (MSN), and ubiquitin C (Ubc), which acted as atypical tumor-suppressors." (PMID 35994202, 2022). "HSP90AB1 is commonly overexpressed in cancers including human OSA." (PMID 33556121, 2021).
cancer (continued). "Studies have suggested that HSP90AA1, HSP90AB1 gene products, and their associated chaperon proteins (Aha1, Cdc37, p23, and Tpr2) as well as HSP90-dependent transcription factor HSF1 are overexpressed in a variety of cancers." (PMID 34109171, 2021). "The six thermogenes include HSP90AA1 and HSPA4, common in thermoresistance and DAMPs/ICD, DNAJB5, the protein product of which has the highest estimated thermostability, and HSPA1A, HSP90AB1, and BAG1, which are implicated in cancer-relevant pathways (underlined)." (PMID 31814876, 2019). "Interestingly, recurrent mutations of genes previously reported to be mutated in cancer: ABL1, BUB1B, NCOR1 (each mutated in three tumours), and CARS, HSP90AB1, NCOA1 (each mutated in two tumours) were uniquely found in recurrent/metastatic NPCs (n=33)." (PMID 28098136, 2017). "In addition, HSP90AB1 has been reported to participate in tumorigenesis, and overexpression of HSP90AB1 has been shown to promote the angiogenesis, metastasis, and differentiation of cancer cells." (PMID 37180757, 2023). "Furthermore, the mRNA levels of cancer factors including heat shock protein 90 alpha family class B member 1 (HSP90AB1), MYC, and insulin like growth factor 1 receptor (IGF1R) were analyzed by quantitative real-time PCR assay to explore the possible antitumor mechanisms of ME." (PMID 36362498, 2022). "These proteins—such as HSP90ab1, eEF1α1, c-Myc and CCT2—play critical roles in cancer cell growth and survival by regulating protein stability, synthesis and transcription." (PMID 40855114, 2025). "Consistent with transcriptomic data, RFC2, HSP90AB1, and YWHAZ were significantly elevated in cancer patients (e.g., RFC2: 18.6 ± 2.1 ng/mL in patients vs. 8.2 ± 1.4 ng/mL in controls, p < 0.001)." (PMID 41164201, 2025). "One of the most studied subfamilies in cancer, the HSPC subfamily (also known as HSP90) presented 2 amp-CNV altered members (HSP90AB1, and TRAP1), and just one del-CNV (HSP90B1)." (PMID 38816397, 2024). "In cancers where HSPA4 expression significantly impacts prognosis, four genes—HSP90AA1, HSPA8, DNAJB1, and HSP90AB1—demonstrated a pronounced correlation." (PMID 38305786, 2024). "Key targets such as TNF, PTGS2, PRKACA, HSP90AB1, RELA, and NFKBIA appeared to be involved in chemical carcinogenesis–receptor activation, pathways in cancer, IL-17 signaling pathway, cholinergic synapse pathway, and regulation of lipolysis in adipocytes." (PMID 39064924, 2024). "HSP90AB1 is one subtype of the HSP90 family, which is related to ATPase activity in cancer cells, and part of its function is to promote cell growth, metastases, invasion, and immune response." (PMID 36362498, 2022). "We treated cells with cisplatin or ME or both, and the expression of cancer pathway factors including MYC1, HSP90AB1, and IGF1R was assessed." (PMID 36362498, 2022). "It was worth noting that the expression levels of CXCR4, PPP3R1, HSP90AB1, CXCL10, and S100A12 were substantially elevated in multiple types of cancer tissues." (PMID 36569892, 2022). "In cluster 2, the key genes CDKN2A, HSP90AB1, TRAF2 and RAF1 are effective agents in cancer pathway." (PMID 29379595, 2017). "The “Pathways in Cancer” involve ITGB1, NOTCH2, and HSP90AB1 genes." (PMID 40621499, 2025). "Crucially, upon evaluating genes that may significantly influence cancer prognosis, HSP90AA1, HSPA8, DNAJB1, and HSP90AB1 manifested pronounced correlations with HSPA4 expression." (PMID 38305786, 2024). "Although there was no shared gene among the three groups in the Cancer-related pathways, three genes were shared between the two malignant groups namely AR, HSP90AB1 and GNAS." (PMID 36686473, 2022). "Importantly, Hsp90ab1 immuno-precipitated latent TGFβ and inactivated TGFβ, whereas MSN interacted with CD44, a cancer stem-cell marker, as well as fibronectin 1, an ECM protein." (PMID 34976221, 2022).
cancer (continued). "Low levels of HSP90AB1/TRAP1, HSPA6/TRAP1, and HSP90AA1/TRAP1 in urine increase the probability of the patient having cancer, whereas low levels of CCT2/HSP90AB1 and HSPB1*HSPA9 in urine are strongly associated with non-cancer groups." (PMID 34692733, 2021). "Activating genes in this branch, first of all TERT, heat shock protein 90 (HSP90AA1, HSP90AB1), importin 7 (IPO7) and p23 (PTGES3) are overexpressed in cancer, while the heat shock protein 70 (HSPA1A) and CHIP ubiquitin ligase (STUB1), both acting as suppressors, are underexpressed." (PMID 31750255, 2019). "Immunoprecipitation revealed that extracellular Hsp90ab1 interacted with latent TGFβ (LAP-TGFβ) as an inhibitor of TGFβ activation, while Hsp90ab1 and Eno1 interacted and suppressed tumor progression via CD44, a cell-adhesion receptor and a cancer stem cell marker." (PMID 34830748, 2021). "The majority of these genes were upregulated in Dual-R versus BTKi-R samples, including heat shock protein genes HSP90AB1 and HSP90AA1 (not shown), which are involved in protein folding and have been shown to promote cancer cell proliferation and migration." (PMID 38326887, 2024).
tumor (104 papers, 2003 to 2026). "HSP90AB1 levels were significantly higher in tumor tissues (p < 0.001) and were negatively linked with miR-497-3p expression (r = −0.526, p < 0.0001)." (PMID 41209079, 2025). "Here, we showed for the first time that the anti-tumor capability of BM CM was linked to the regulatory network of Hsp90ab1, Eno1, Ubc, CD44, and LAP-TGFβ." (PMID 34830748, 2021). "We carried out preliminary genetic characterisation by whole exome sequencing and detected tumor specific mutations in Hsp90ab1, Ccnb3 and RhoA." (PMID 31013298, 2019). "Importantly, tumors derived from Villin-CreERT2, Usp22flox mice containing a mutation in the Adenomatous Polyposis Coli (APC) tumor suppressor gene (APC1638N/+) similarly displayed decreased HSP90AB1 levels compared to the Usp22 wild type control tumors." (PMID 31801945, 2019). "Then ATP6AP1, PSMD14 and HSP90AB1 were selected to verify the expression in 63 cases of tumor tissues and the adjacent non-tumor tissues." (PMID 38327651, 2023). "Then, we selected ATP6AP1, PSMD14 and HSP90AB1 as the candidate genes and verified the expressions in 63 cases of tumor tissues and the adjacent non-tumor tissues." (PMID 38327651, 2023). "To access the mechanism of anti-tumor, anti-inflammatory actions of YS MSC CM, we selected five tumor suppressors (Hsp90ab1, calreticulin, histone H4, polyubiquitin C, and enolase 1) based on our previous whole-genome proteomics analysis." (PMID 35804814, 2022). "Whole-genome proteomics predicted enolase 1 (Eno1), Hsp90ab1, Eef2, and vinculin as extracellular tumor suppressors." (PMID 35547745, 2022). "In immunoprecipitated proteins using an antibody against Hsp90ab1, mass spectrometry-based proteomics identified 1597 proteins in tumor cells and their ECM." (PMID 35804814, 2022). "Osteoclast secretome-derived Hsp90ab1 and Eno1 inhibited tumor progression by suppressing TGF-ß signaling and interacting with CD44, facilitating tumor cell killing by natural killer (NK) cells." (PMID 35994202, 2022). "To elucidate the mechanism of the anti-tumor action of Hsp90ab1 and MSN, we evaluated their downstream protumorigenic genes such as TGFβ, Runx2, Snail, and MMP9, as well as PDL1 24 that inhibits immune responses and KDM3A 25 that regulates histone methylation." (PMID 34976221, 2022). "It was unexpected that the proteins such as Hsp90ab1, Eno1, Eef2, and vinculin were enriched in the secretome since they are considered tumor promoters intracellularly 35-38." (PMID 35547745, 2022). "These newly identified tumor suppressors, such as extracellular Eno1, Hsp90ab1, Eef2, and vinculin, downregulated Kdm3a, a histone demethylase, as well as the downstream oncogenic genes 21-24." (PMID 35547745, 2022). "To assess the potential mechanism of tumor-suppressive action of Hsp90ab1 and MSN, we conducted an immunoprecipitation assay." (PMID 34976221, 2022). "Akt CM also showed the tumor selectivity of 2.41 ± 0.70 and Hsp90ab1 and Calr gave a higher tumor selectivity than Ppib." (PMID 33859739, 2021). "Immunoprecipitation revealed that Hsp90ab1 and Eno1 interact and inhibit the progression of tumor cells by blocking TGFβ activation and interacting with CD44, a cell-adhesion receptor." (PMID 34830748, 2021). "Using three tumor cells (MDA-MB-231, 4T1.2 and EO771) and two normal cells (MSCs and MLO-A5 osteocytes), we determined tumor selectivity for Lrp5 CM, Akt CM, Hsp90ab1, Calr and Ppib." (PMID 33859739, 2021). "To test the anti-tumor action of extracellular Hsp90ab1, we employed recombinant Hsp90ab1 (Hsp90 beta) together with recombinant Hsp90aa1 (Hsp90 alpha) as a control." (PMID 34830748, 2021). "Hsp90ab1 reduced the scratch-based migration and downregulated tumor-promoting genes Lrp5, MMP9, Runx2 and Snail in 4T1.2 cells." (PMID 33859739, 2021). "We have previously shown that iTSC CM, derived from tumor cells, is enriched with atypical tumor-suppressing proteins, including Hsp90ab1, Eno1, and Ubc." (PMID 34830748, 2021).
tumor (continued). "Four heat shock proteins (Hspa5, Hsp90ab1, Hspa8 and Hsp90aa1) were included in the top candidate list and Hsp90ab1 was predicted to be one of the most influential tumor suppressors, as well as calreticulin (Calr) and peptidylprolyl isomerase B (Ppib)." (PMID 33859739, 2021). "Three atypical tumor-suppressing proteins, Hsp90ab1, Eno1, and Ubc, focused in this study, are moonlighting proteins with contrasting roles in the intracellular and extracellular domains." (PMID 34830748, 2021). "The results thus indicated that Hsp90ab1, Eno1, and Ubc were involved in the anti-tumor actions of BM CM." (PMID 34830748, 2021). "The tumor-suppressing action of extracellular HSP90ab1 in MSC-derived CM was the opposite to the action of its intracellular counterpart." (PMID 33859739, 2021). "As a potential anti-tumor mechanism of BML284-treated osteoclast-derived CM (BM CM), we examined the role of three atypical tumor-suppressing proteins: Hsp90ab1, enolase 1 (Eno1), and polyubiquitin C (Ubc)." (PMID 34830748, 2021). "Whole-genome proteomics analysis predicted the tumor-suppressing action of Hsp90ab1, calreticulin and peptidylprolyl isomerase B (Ppib)." (PMID 33859739, 2021). "Among these, Hsp90ab1 and XPO5 have been previously associated with poor prognosis and tumor-suppressor properties in GC." (PMID 32849808, 2020). "In BRAC tissues, the expression of HSP90AA1, HSP90AB1, and HSP90B1 was conformably correlated with the expression of biomarkers of some lineages of CD4+ helper T (Th) cells and tumor-associated macrophages (TAMs)." (PMID 33145341, 2020). "To quantify cell growth in the tumor samples, we visualized Hsp90ab1 and Ki-67 expression in paraffin-embedded xenograft tumors." (PMID 30305727, 2019). "Then we found that the mRNA expression levels of HSP90AB1 were significantly higher in tumor tissues than normal tissues (fold-change = 1.83) in 28 pairs of colorectal tissue samples." (PMID 27756247, 2016). "Meanwhile, the C allele of rs2282151 was associated with increased expression level of HSP90AB1, which was expressed higher in CRC tumor tissue than normal tissue." (PMID 27756247, 2016). "Beside the eQTL signals, we found significantly higher expression levels of HSP90AB1 in CRC tumor than paired normal samples in all three online databases." (PMID 27756247, 2016). "Several studies have reported the individual expression pattern and function of each hub (TK1, CSNK2B, VIM, YWHAB and HSP90AB1) in different tumors and tumor models in vitro." (PMID 27527857, 2016). "Heat shock protein 90 kDa alpha, class B member 1 (Hsp90AB1) is highly conserved ATP-dependent molecular chaperone, and over-expressed in a variety of tumor cells." (PMID 26903158, 2016). "Among them, nitric-oxide synthase regulator activity, referred to hsp90aa1 and hsp90ab1 proteins, is particularly interesting, since the nitric oxide (NO) pathway appears to play a key role in tumor angiogenesis and spread." (PMID 27050372, 2016). "Concerning the genes related to tumor progression, we found HSP90AB1, GRB2, ERBB2/3, EIF4A3, HDGF, and CSNK2B." (PMID 25625699, 2015). "We identified ATP6AP1, PSMD14 and HSP90AB1, which were exactly highly expressed in tumor tissue." (PMID 38327651, 2023). "The results showed that ATP6AP1, PSMD14, HSP90AB1 were generally highly expressed in tumor tissues." (PMID 38327651, 2023). "In recent years, studies concerning HSP90AB1 have identified its function in neoplasms." (PMID 38327651, 2023). "Besides, in mast cells, two NPA genes HSP90AA1 and HSP90AB1 were up-regulated in tumor tissues, whereas BIRC3 was down-regulated." (PMID 38149248, 2023).